IGF1 (insulin like growth factor 1)
Diseases named in the same sentence as IGF1 in open-access papers (continued):
Sharing a sentence is not in itself a finding about the gene and the disease.
Hypertension (continued). "Future studies are recommended to confirm the roles of oxidative stress and antioxidants for insulin- and IGF-1-mediated cardiovascular dysfunction in the elderly population with hypertension." (PMID 34203897, 2021). "In contrast, the cerebral cortex Bcl-2 family-related and IGF-1-related pro-survival pathways were suppressed by early aged hypertension and were enhanced after exercise training." (PMID 34432648, 2021). "In order to study the effects of the process of aging on vascular endothelial dysfunction in hypertension, the insulin- and IGF-1-mediated vasorelaxation was evaluated in endothelium-intact and denuded rings among the four groups." (PMID 34203897, 2021). "IGF-1 regulates Endothelin-1 (ET-1), which has been found to have an important role in vascular hypertrophy and proliferation, leading to hypertension." (PMID 34198576, 2021). "Consistently, we found that the coexistence of aging and hypertension induced more severe endothelial dysfunction in response to insulin and IGF-1 in older SHRs." (PMID 34203897, 2021). "This study aimed to investigate the aging-related endothelial dysfunction mediated by insulin and insulin-like growth factor-1 (IGF-1) and antioxidant deficiency in hypertension." (PMID 34203897, 2021). "Newborns whose mother had hypertension during pregnancy tend to have insufficient supply of nutrition during pregnancy and reduced level of insulin-like growth factor 1 (IGF-1), an important stimulus for fetal linear growth and weight gain." (PMID 32817708, 2020). "High blood pressure can reduce IGF-1 binding protein, which can increase IGF-1 activity and increase the risk of PC." (PMID 33050163, 2020). "This study aimed to investigate the effects of PCA administration on vascular endothelial function, mediated by insulin and insulin-like growth factor-1 (IGF-1), and antioxidant activities in aging hypertension." (PMID 30934575, 2019). "In conclusion, the 12 weeks of PCA administration remarkably improved the endothelium-dependent vasorelaxation induced by insulin and IGF-1 in aging hypertension through enhancing the PI3K–NOS–NO pathway." (PMID 30934575, 2019). "Hypertension and aberrant IGF1 receptor signaling are highlighted as the important contributors to IGF1-related CVD events." (PMID 31327319, 2019). "Circulating IGF1 is known to induce vasodilation, which contributes to the regulation of arterial BP and vascular tone, while deletion of IGF1 in mice enhanced mechanisms of vasoconstriction leading to hypertension." (PMID 31327319, 2019). "Previous research has reported that the vascular actions of insulin and IGF-1 are pathologically altered and impaired in cardiovascular disorders, such as hypertension and obesity." (PMID 30934575, 2019). "In conclusion, our study demonstrated that 12 weeks of PCA administration remarkably improved the endothelium-dependent vasorelaxation induced by insulin and IGF-1 in aging hypertension through enhancing the PI3K–NOS–NO pathway." (PMID 30934575, 2019). "In clinical studies, substitution with IGF1 was often followed by resolution of hypertension and improvement of the intima-media thickness of the arterial vessel wall." (PMID 31327319, 2019). "LRA showed that 25(OH)D3, IGF-1, FBG, TC, TT3, TT4, and high blood pressure were associated with thyroid nodules." (PMID 31077177, 2019). "Logistic regression analysis showed that 25(OH)D3, IGF-1, FBG, TC, TT3, TT4, and high blood pressure were associated with thyroid nodules as well." (PMID 31077177, 2019). "In this study, swim training or insulin-like growth factor-1 (IGF-1) was used as physiological stress whereas hypertension developed in SHR or phenylephrine (PE) was used as pathological stress." (PMID 25753319, 2015). "Research in the field of hormones like testosterone, prolactin and IGF-1 as individual biomarkers and putative predictors of clinical outcomes (e.g., hypertension, depression, inflammation) has been especially successful." (PMID 24886498, 2014).
Hypertension (continued). "The aim of the present study was to determine the effect of chronic alcohol consumption on IGF-1 myocardial expression and to compare this expression in cases of hypertension and other cardiac diseases." (PMID 25984322, 2013). "This study evaluates IGF-1 expression in myocardial tissue in human donors with chronic alcohol consumption in comparison to healthy donors and also with donors with hypertension or other cardiac diseases using an immunohistochemical IGF-1-specific assay." (PMID 25984322, 2013). "The main objective in the present study was to evaluate myocardium IGF-1 expression in human organ donors and determine the effect of chronic alcohol consumption, the presence of CMP, hypertension or other causes of myocardial damage." (PMID 25984322, 2013). "To control for confounding factors, we then performed a multiple regression analysis using IGF-1 level as dependent variable and age, sex, body mass index (BMI), smoking, hypertension and blood glucose level as covariates." (PMID 19460140, 2009). "Therefore, IGF-1 has a tight connection to hypertension in patients with RA, being a possibly valuable predictor for CVD development." (PMID 41010664, 2025). "IGF-1 influences this phenotypic switching toward a protective and adaptive state, thereby enhancing the structural integrity and function of blood vessels under stress conditions such as hypertension." (PMID 39271571, 2025). "The IGF-1 has strong vasorelaxant properties and increases IGF-1 signaling in hypertension." (PMID 38540997, 2024). "Hypertension is also related to low vascular relaxation response to IGF-1." (PMID 38540997, 2024). "Low serum IGF-1 levels predict the development of early cardiovascular disorders and hypertension." (PMID 38540997, 2024). "Several studies have focused on the effects of aging and IGF-1 deficiency on adaptive vessel remodeling in response to hypertension, showing that adaptive hypertrophy and ECM remodeling in larger arteries and penetrating arterioles is impaired in aged and circulating IGF-1-deficient animals." (PMID 38425784, 2024). "Previous reports on the relationship between IGF-1 and blood pressure regulation in hypertensive disorders are conflicting, with some studies indicating higher levels of IGF-1 in people with hypertension, yet several large cross-sectional studies demonstrating a inverse relationship." (PMID 38952391, 2024). "Hypertension induction in IGF-1 knockout mice revealed impaired cerebrovascular autoregulation." (PMID 37358957, 2023). "Decreased circulating IGF-1 levels in rodent models are also associated with increased BBB permeability, pathological microvascular remodeling, increased microvascular fragility, and increased susceptibility to the hypertension-induced development of CMHs." (PMID 35356301, 2022). "The structural integrity of cerebral arteries is also affected in Igf1 f/f mice with decreasing elastin content and limited adaptation to hypertension and IGF-1 treatment of middle-aged rats prior to cerebral artery occlusion has been shown to improve the integrity of the blood–brain barrier." (PMID 35563873, 2022). "IGF-1 reduced hypertension in pre-clinical models of hypertension." (PMID 35631301, 2022). "Moreover, it has been reported that insulin and insulin-like growth factor 1 (IGF-1) are independent predictors of LVH in patients with hypertension." (PMID 35369303, 2022). "First, although we clearly demonstrated that IGF-1 attenuated cardiac fibrosis in an AngII-infusion mouse model, cardiac fibrosis is already present in pathological conditions, such as hypertension or myocardial infarction, when antifibrotic treatment is started in humans." (PMID 34244467, 2021). "This implied that the reduced level of antioxidants might involve in the impairments of insulin- and IGF-1-mediated vasorelaxation in hypertension." (PMID 34203897, 2021).
Hypertension (continued). "It is important to note that age-related endocrine changes, specifically, the age-related decline in IGF-1 may play a central role in the development of age-related, hypertension-induced formation of microbleeds." (PMID 33011936, 2021). "In addition, multivariate analysis, such as that performed by Casini, showed that hypertension and IGF-1 levels were determinants of left ventricular hypertrophy." (PMID 33869029, 2021). "Age, BMI, disease duration, and hypertension but not GH or IGF-1 levels are associated clinical factors." (PMID 32148485, 2020). "Importantly, the relation between these proteins changes with hypertension, demonstrating its intimate connection with low IGF1." (PMID 31327319, 2019). "Indeed, the patients with low IGF1 demonstrated higher BP measures at baseline and a significant increase in treatment for hypertension at the prospective follow-up." (PMID 31327319, 2019). "The variables included FBG, TC, TT3, TT4, hypertension, 25(OH)D3, and IGF-1." (PMID 31077177, 2019). "The profile of new CVD events consisted of the established complications of hypertension including ischemic stroke, atrial fibrillation, and aorta aneurysm, which indicated that hypertension was an essential clinical sign of IGF1-related CVD of the studied patients." (PMID 31327319, 2019). "Also, the diminished vasorelaxant effects of insulin and IGF-1 have been found in the development of hypertension." (PMID 30934575, 2019). "Treatment with TNF-a inhibitors is suggested to improve hypertension through an endothelium-dependent mechanism, which could indicate a contribution of increasing IGF1 levels." (PMID 31327319, 2019). "Thus, it is significant that hypertension‐induced cerebrovascular oxidative stress and MMP activation were increased in IGF‐1‐deficient mice." (PMID 28295976, 2017). "The decreased transcription of Igf1 in ISIAH adrenals is in a good agreement with the observation that IGF1 expression may be significantly decreased in the presence of hypertension." (PMID 28105924, 2016). "Mats Halldin proved in his study that high blood pressure and WC were independent risk factors for LVH and argued that the LVH might result from the changes in the mediated IGF-1 and IGF-Binding Protein-1." (PMID 26772538, 2016). "This is in concordance to what has been observed in previous studies, in which low levels of IGF-1 were found to be associated with hypertension in subjects without other cardiovascular diseases." (PMID 25984322, 2013). "Experimental studies in IGF-1-deficient or IGF-1-depleted animal models consistently show an increased burden of CMBs, impaired autoregulatory function and neurovascular uncoupling, pathological structural adaptation to hypertension and heightened vulnerability to hemorrhagic injury." (PMID 41157242, 2025). "One potential IGF-1 responsive target is vascular smooth muscle cells (VSMCs), the contractile cells on large- and medium-sized blood vessels that regulate blood pressure, organ perfusion, and vascular integrity in response to environmental stressors such as hypertension." (PMID 38425784, 2024). "Moreover, in young people with hypertension, faster biological development has also been observed, characterized by the predominance of the catabolic process, including a reduction in the level of IGF-1." (PMID 38540997, 2024). "Our study revealed that plasma IGF-1 levels may be a risk factor for IVS thickening in patients with/without hypertension." (PMID 36568107, 2022). "Even though insulin/IGF-1 may not play a role in hypertension, insulin/IGF-1 resistance seems to cause hypertension, especially when IGF-1 is associated with excessive NO levels in both vessels and the heart." (PMID 35454166, 2022). "However, in spite of the shared anatomical origins and important functional and structural similarities between the retinal and cerebral microvasculature, we found that IGF-1 deficiency did not exacerbate hypertension-induced microbleeds in the retina." (PMID 35356301, 2022).
Hypertension (continued). "Moreover, hormonal factors induced by fetal growth restriction, such as high levels of insulin-like growth factor-1 (IGF-1), as well as protein restriction in the maternal diet, are probably involved in the onset of high blood pressure in SGA newborns or those with FGR." (PMID 35886134, 2022). "The occurrence of hypertension may be due to the comprehensive effects of long-term high levels of GH/IGF-1 on the cardiovascular system, kidneys and other organs, which ultimately leads to an increase in extracellular fluid volume and peripheral vascular resistance." (PMID 33869029, 2021). "However, in aging hypertension, the ways insulin and IGF-1 influence the cardiovascular dysfunction remain unclear." (PMID 30934575, 2019). "These protective effects further underscore the importance of IGF-1 in maintaining brain health and preventing CSVD, particularly in the context of aging and hypertension." (PMID 39271571, 2025). "Here, we studied the relationship between leukocyte IGF-1/IGF-1R mRNA, IGF-1R protein expression, plasma IGF-1 levels, and hypertension-mediated organ damage (HMOD) parameters in pediatric PH patients." (PMID 38540997, 2024). "In addition, Tucsek and colleagues reported that hypertension was associated with a reduced synaptic density in the mouse hippocampus and with the down-regulation of several genes that are neuroprotective, such as BDNF and Igf1, or regulate postsynaptic signal transduction events, such as Homer1." (PMID 39457698, 2024). "A cross-sectional study compared the changes in plasma concentrations of cGP, IGF-1, and IGFBP-3 between healthy women and women with hypertension 6 years post-partum." (PMID 36770687, 2023). "Mechanistically, age-induced reduction in IGF-1 (insulin-like growth factor -1) signaling and reactive oxygen species-mediated activation of MMPs (Matrix Metalloproteinases) in the cerebrovasculature could make the cerebral blood vessels more vulnerable to hypertension-induced rupture." (PMID 35547620, 2022). "This suggested that the aging hypertension evoked the decreased activation of PI3K and NOS, partly resulting in the impairments of NO production and insulin- and IGF-1-induced vasorelaxation." (PMID 30934575, 2019). "The other patient was a 58-year-old woman with a microadenoma as well, and severe hypertension who initiated primary therapy with PEGV assuming a faster and more effective control of IGF-1 excess." (PMID 31460622, 2019). "Low serum IGF1 precedes and predicts the development of early CVD events due to a tight connection with hypertension, which is important for future management of RA patients." (PMID 31327319, 2019). "Logistic regression analysis showed that there was a negative correlation between thyroid nodules and levels of 25(OH)D3, IGF-1, TT3, as well as a positive correlation with FBG, TC, TT4, and hypertension." (PMID 31077177, 2019). "In contrast, GWE exhibited a negative correlation with both age and 1.5 × ULN IGF-1, while it showed a positive correlation with a history of hypertension." (PMID 41488995, 2026). "Our findings showed that GWW had a positive correlation with age and 1.5 × ULN IGF-1 and a negative correlation with a history of hypertension." (PMID 41488995, 2026). "Our previous study suggested that GH/IGF-1 could regulate the components of RAAS, promote sodium and water reabsorption, induce the increase of extracellular fluid, and even contribute to hypertension." (PMID 40860776, 2025). "One of the remaining questions is whether defective IGF-1 signaling in cerebrovascular VSMCs in aging prevents the adoption of protective VSMC phenotypes in the context of age-related challenges, such as hypertension and inflammation." (PMID 38425784, 2024). "Studies have shown that IGF-1 levels are higher in patients with hypertension than in those without." (PMID 34078313, 2021). "Previous studies that used CMR have demonstrated that LVMi is not correlated with IGF-1 levels, age, disease duration, or hypertension." (PMID 32148485, 2020).
Hypertension (continued). "In hypertension, IGF1 was no longer responsible for intracellular activation and lost its correlation to IRS1/2 adaptor proteins." (PMID 31327319, 2019). "Thyroid nodule was analyzed by LRA to reveal the effects of the single factors on the thyroid nodules, including sex, age, 25(OH)D3, IGF-1, FBG, blood lipid, WC, uric acid, thyroid function, liver function, BMI, HbA1c, HOMA-IR, hypertension, smoking history, and drinking history." (PMID 31077177, 2019). "Instead, novel correlations between IGF1R, IRS1, IRS2, and insulin appeared with hypertension demonstrating that IGF1 is no longer responsible for activation of intracellular processes through IGF1R." (PMID 31327319, 2019). "Therefore, 25(OH)D3, IGF-1 and TT3 were negatively correlated with thyroid nodules, while FBG, TC, TT4, and hypertension were positively correlated with thyroid nodules." (PMID 31077177, 2019). "Serum 25(OH)D3, IGF-1, fasting blood glucose (FBG), total cholesterol (TC), waist circumference (WC), total triiodothyronine (TT3), total thyroxine (TT4), hypertension history, and drinking history were significantly different between the nodules group and the control group (P < 0.05)." (PMID 31077177, 2019). "We also observed a downward trend in IGF-1 myocardial expression in the other groups of donors with hypertension and other cardiac diseases, although without achieving significant differences compared to controls." (PMID 25984322, 2013). "Insulin also increases the release of IGF-1, which can lead to hypertension as a result of nonstriated-muscle hypertrophy." (PMID 22262974, 2012). "Serum IGF-1 levels are high in hypertensive adult patients, possibly because of the induction of several adaptive responses, such as ventricular hypertrophy and vascular remodeling Human studies on the role of IGF-1 in hypertension are limited, and results conflicted." (PMID 38540997, 2024). "In previous studies using circulating IGF-1 knockdown animals and a similar hypertension paradigm to ours, autoregulatory responses were not different in normotensive circulating IGF-1 knockdown mice vs. controls; defects between groups were only seen in hypertensive animals." (PMID 38425784, 2024). "Overall, IGF-1 has a central role in regulation of CBF by contributing to pressure- and flow-dependent responses of cerebral arteries, plays a role in structural adaptation to hypertension, and contributes to adaptive ECM changes and in ECM-related gene expression." (PMID 36755922, 2023). "Autoregulatory impairment was most pronounced in hypertensive IGF-1 deficient mice, who also failed to exhibit the protective increase in myogenic tone and protective increases in TRPC6 channel expression that accompany hypertension in control mice." (PMID 36755922, 2023). "However, the effectiveness of PCA administration on aging hypertension with regard to the vasorelaxant effects of insulin and IGF-1 and antioxidant activities has not been fully investigated." (PMID 30934575, 2019). "Hypertension‐induced changes in base of support did not correlate with IGF‐1 status." (PMID 28295976, 2017). "While IGF‐1 deficiency does not appear to be associated with marked changes in MMP expression, it was found to exacerbate hypertension‐induced oxidative stress in cerebral arteries, presenting redox‐sensitive MMP activation as a potential mechanism responsible for the observed phenotype." (PMID 28295976, 2017). "We further demonstrated low IGF-1 SDS is in negative correlation with hypertriglyceridemia independent of age, gender and pubertal status, but it was not in statistically significant association with hypertension." (PMID 27343122, 2016). "However, our functional data showing physiological defects in normotensive Igf1r KD animals suggest that IGF-1 may also be important for basal maintenance of vascular wall integrity, not just for adaptive responses to hypertension." (PMID 38425784, 2024).